PBRM1 (polybromo 1)
Diseases named in the same sentence as PBRM1 in open-access papers (continued):
Sharing a sentence is not in itself a finding about the gene and the disease.
cancer (continued). "Inactivating mutations in PBRM1, SETD2, KDM5C and BAP1 tend to be focal in the tumors, so therapies that are designed to exploit the weakness induced by mutation of an individual gene could be problematic since it cannot treat the remaining cancer cells free of that mutation." (PMID 30355451, 2018). "Strikingly, both sample sets shared six genes in their ‘top 20’ list of most frequently lost ‘Cancer census genes’ (i.e. EP300, SETD2, PBRM1, CHEK2, MKL1 and MAPK1)." (PMID 29371938, 2017). "Six other ‘Cancer census genes’ however, were listed among the most frequently lost ones, both in the TCGA- and LP-WGS-dataset (i.e. EP300, SETD2, PBRM1, CHEK2, MKL1 and MAPK1)." (PMID 29371938, 2017). "Mutations in these genes appear to be either specific to ICC, as is the case of IDH1 and IDH2 (p=0.0005), or cluster within this cancer type as is the case for ARID1A, BAP1, and PBRM1 that were found in 34.3% (24/70) of ICC." (PMID 24867389, 2014). "We also found that PBRM1 mRNA levels showed no obvious differences between normal and cancer tissues across TCGA cancer types." (PMID 39375538, 2024). "We found a single report linking PBRM1 and NRF2 activities in cancer." (PMID 38358974, 2024). "PBRM1 represses, as well as activates, IFN pathway genes in different cancer cells." (PMID 36445328, 2023). "The polybromo-1 (PBRM1) chromatin-targeting subunit of the SWI/SNF PBAF chromatin remodeling complex drives DNA damage resistance and immune evasion in certain cancer cells through mechanisms that remain unclear." (PMID 36445328, 2023). "No consistent associations with cancer-specific survival (CSS) have been found for VHL, PBRM1 and MTOR18–22." (PMID 35444164, 2022). "Despite the extensive development of high‐throughput sequencing of cancer genomes, key candidates activated by PBRM1 in cytokine production and inflammation pathways are not known." (PMID 34535962, 2021). "To validate our hypothesis, we decided to examine the ISGF3 protein levels in ccRCC cancer cells with IHC and correlate their protein levels with the protein levels of BAP1, PBRM1, and SETD2." (PMID 30355451, 2018). "The Cancer Genome Atlas Research Network supports the fundamental role of oxygen-sensing genes (VHL) and chromatin remodeling genes (PBRM1, BAP1 and SETD2) in RCC tumorigenesis, highlighting their potential as prognostic biomarkers and/or future therapeutic targets." (PMID 26452128, 2015). "Patients who have KIRC and THCA tumors were mostly classified into two PRECISE clusters and the PBRM1 gene that is a novel drug target for KIRC was found in patients located in one of the clusters, which indicates that PRECISE effectively classified subtypes across cancers." (PMID 30297783, 2018). "Since our hypothesis is that BAP1, PBRM1, KDM5C, SETD2 are critical to maintain the expression and/or function of ISGF3 subunits in the ccRCC cancer cells, we concluded that mRNA levels in the bulk tumors from the TCGA dataset are not suitable for our validation experiments." (PMID 30355451, 2018). "Co-occurring of genetic mutations in cancers with KDM5C alterations were not uncommon in both early-stage and advanced stage cohort and some of them are prevalent driver genes (e.g., LRP2, KMT2C, PBRM1, NOTCH1, FAT1, SETD2, NSD1, etc.), while their clinical significance remained undetermined." (PMID 33953726, 2021). "Notably, prior work has suggested thatBAP1, PBRM1, and ARID1Adeficiency all result in sensitivity to EZH2 inhibition across cancer types; the association of ARID1Amethylation with IDH mutation opens the question of whether EZH2 inhibition mightalso be effective in this subtype." (PMID 28297679, 2017). "Our analysis revealed a strong negative correlation between PBRM1 E27 PSI and RBFOX2 expression in most cancer types." (PMID 39375538, 2024).
cancer (continued). "According to the subgroup analyses, PBRM1-MUT showed an apparent survival advantage over PBRM1-WT, regardless of age, sex, cancer type (except for BLCA), drug class, and TMB level (except for TMB high) (p > .05)." (PMID 36699446, 2022).
adenocarcinoma (4 papers, 2021 to 2023). A common cancer characterized by the presence of malignant glandular cells. "This study aimed to investigate the clinical relevance of immunohistochemical expression of proteins of the SWI/SNF complex, SMARCA2, SMARCA4 SMARCB1, ARID1A, ARID1B, and PBRM1 in 477 adenocarcinomas of the stomach and gastroesophageal junction." (PMID 34359794, 2021). "His adenocarcinoma was HepPar1-positive and showed loss of SMARCA2 and PBRM1 (data not shown)." (PMID 33506327, 2021).
infection (3 papers, 2017 to 2025). The state of being infected such as from the introduction of a foreign agent such as serum, vaccine, antigenic substance or organism. "PBRM1 re-expression in KD-PBRM1 cells showed favorable infection efficiency." (PMID 28846693, 2017).
genetic disorders (2 papers, 2022 to 2023). "Some of the ccRCCs associate with genetic disorders, the most prevalent being the von Hyppel-Lindau (VHL) gene (located on the short arm of chromosome 3) and the protein polybromo-1 (PBRM-1) gene (also located on the short arm of the chromosome 3)." (PMID 37176098, 2023). "The two most prevalent genetic disorders are the protein polybromo-1 (PBRM-1) gene and the von Hippel-Lindau (VHL) gene." (PMID 36627997, 2022).
prostate (1 paper, 2019). "Taken together, these results suggest that PBRM1 localization and, specifically, both its nuclear and cytoplasmic localizations, may be related to prostate tumorigenesis." (PMID 31212728, 2019).
PBRM1 also shares sentences with these, for which no sentence is quoted: colon adenocarcinoma (4 papers); bladder urothelial carcinoma (2); Secretory Meningioma (2); small cell carcinoma of the ovary (2); acute myeloid leukemia (1); Alzheimer disease (1); ampullary adenocarcinoma (1); atrial fibrillation (1); autism (1); benign prostatic hyperplasia (1); bladder tumours (1); breast invasive carcinoma (1); cervical cancer (1); cervical squamous cell carcinoma (1); chronic hepatitis (1); Clear Cell Meningioma (1); Coffin-Siris syndrome (1); colon cancer (1); connective tissue tumors (1); Crohn disease (1); duodenal adenocarcinoma (1); embryonic carcinoma (1); esophageal carcinoma (1); gastric adenoma (1); glioblastoma (1); head and neck squamous cell carcinoma (1); head/neck cancers (1); hemangioblastoma (1); Hepatitis (1); hepatitis viral ( (1).
A further 30 diseases each share a sentence with PBRM1 in 1 paper.